MTOR (mechanistic target of rapamycin kinase)
Diseases named in the same sentence as MTOR in open-access papers (continued):
Sharing a sentence is not in itself a finding about the gene and the disease.
melanoma (continued). "Indeed, multiple groups have shown that interfering with mTOR function in BMDC enhances vaccine-induced CD8+ T cell responses and immunologic control of established B16 melanomas." (PMID 29209327, 2017). "Thus, our data provide ample evidence that cryptolepine-induced inhibition of mTOR signaling and SIRT1 protein levels resulted in reduction of PGC-1α protein levels and mitochondrial biogenesis in cryptolepine-treated melanoma cells." (PMID 28473727, 2017). "Low levels of MITF and high levels of AXL may predict melanoma resistance to BRAFi, and the resistance may involve (re)activation of MAPK or PI3K/mTOR signaling." (PMID 26918352, 2016). "In addition, fisetin inhibited melanoma cell proliferation and tumor growth by downregulating the PI3K/AKT/mTOR signaling pathway." (PMID 26517521, 2016). "Only on Me23, the combination of PLX4720 with GDC-0941, or AZD8055 achieved synergistic growth inhibitory effect indicating that, for this particular melanoma, concurrent suppression of RAF/MAPK/ERK pathway is necessary to affect growth when only PI3K or mTOR signaling is abrogated." (PMID 25742786, 2015). "The pathways downstream of NRAS that could be targeted simultaneously in NRAS-mutant melanoma include, but are not limited to, MEK, PI3K/mTOR, and cell-cycle-related targets." (PMID 24743024, 2014). "We asked whether concomitant resistance to MEK, PI3K/mTOR inhibitors and to the death receptor ligand TRAIL is frequent in human melanoma." (PMID 25275595, 2014). "In this model, growth of melanoma could be inhibited by combined treatment with PD325901 (MEK inhibitor) and rapamycin (mTOR inhibitor)." (PMID 24743024, 2014). "However, this study adds evidence to the importance of the MAPK and PI3K/mTOR pathway in NRAS mutant cancer and supports that these findings are not limited to NRAS mutant melanoma cells." (PMID 25277205, 2014). "Although trials of single agent mTOR inhibition produced a 0% stable disease rate, preliminary results in a phase I trial of CCI-779 and HCQ in patients with all solid tumors showed a 74% stable disease rate in melanoma patients at first restaging." (PMID 23383069, 2013). "Human melanomas frequently exhibit dysregulation of crucial signal transduction pathways and their components, including those of the Ras/Raf/MEK/MAPK and PI3K/AKT/mTOR pathways, each of which constitute central regulators of cell growth, survival, and other critical parameters of oncogenesis." (PMID 23648148, 2013). "We propose that iRF limits melanoma aggressiveness by negative modulation of Src kinase, mTor and HH pathways, as well as metaloproteinases." (PMID 23342114, 2013). "Analyzing the mutational spectrum found in SCC, BCC and melanoma, respectively, AKT/mTOR signaling at a first glance does not seem to play a prevalent role in skin carcinogenesis." (PMID 23887651, 2013). "This suggests that administration of a combination of an mTOR inhibitor (rapamycin or CCI-779) and BAY43-9006 could be an especially effective approach to therapy of melanoma." (PMID 16255777, 2005). "This is supported by evidence showing that inhibiting AKT or mTOR, either pharmacologically or genetically, fails to suppress cell growth or induce cell cycle arrest, even in the presence of elevated pAKT levels across melanoma cell lines." (PMID 41596686, 2026). "Therefore, this study investigated whether BA and BE mediate autophagy through the PI3K/AKT/mTOR and MAPK signaling pathways, induce apoptosis, and thereby exert anti-melanoma effects." (PMID 41596235, 2026). "Combining BRAFi + MEKi with mTOR inhibitors (e.g., rapamycin) suppressed NR2F1-driven MRD and delayed relapse, suggesting that targeting NR2F1 or downstream pathways in DTP cells is a potentially viable strategy to overcome dormancy-like resistance to melanoma therapy." (PMID 40955667, 2025).
melanoma (continued). "Likewise, LPS from Gram-negative bacteria activates TLR4, triggering the PI3K/AKT/mTOR pathway and thereby increasing melanoma cell proliferation, invasion, and metastatic potential." (PMID 41030253, 2025). "In vivo studies demonstrated that low-dose artemisinin inhibited UM melanoma tumor growth by up to 50%, whereas a 75% reduction was observed in high-dose animals by a mechanism related to PI3K/AKT/mTOR signaling, suggesting that its antitumor effects may occur by targeting this pathway." (PMID 41160271, 2025). "Intriguingly, TTD melanoma cells exhibited reduced proliferation and an increased signature of the melanocyte lineage factor MITF, along with a strong basal upregulation of REDD2, an inhibitor of the mTOR/S6K/4EBP1-dependent messenger RNA (mRNA) translation machinery." (PMID 40918647, 2025). "The dysregulated paracrine renin–angiotensin system, especially through the binding of ATII to AT1R, may enhance melanoma CSC properties by activating the Ras/RAF/MAPK/ERK and PI3K/AKT/mTOR pathways, ultimately leading to the increased expression of CSC markers and self-renewal capacity." (PMID 39941158, 2025). "Possible future steps could be the quantification of CXCR4 and markers of cell invasiveness, autophagy, and mTOR signalling, in biopsies from metastatic and non-metastatic melanoma patients, by immunohistochemistry." (PMID 38474372, 2024). "In addition, the gene PIK3CA, which encodes phosphatidylino-sitol 3-kinases (PI3ks), has been implicated in the modulation of ferroptosis in various diseases, including melanoma, rheumatoid arthritis, and lung injury, primarily via the PI3K/AKT/mTOR signaling pathway." (PMID 38402377, 2024). "In addition, mTOR activation appears to be independent of AKT signaling in other melanoma cell lines." (PMID 38771435, 2024). "Furthermore, celastrol can inhibit the growth of B16 melanoma cells and induce apoptotic cell death via activation of the reactive oxygen species (ROS) dependent mitochondrial pathway and suppression of the PI3K/AKT/mTOR signaling." (PMID 38771435, 2024). "One or more combinations of MEK inhibitors with either anisomycin, rapamycin, chloroquine/bafilomycin, and cytochalasin modulate p38 activation, mTOR phosphorylation, autophagy, and actin polymerization, respectively, and they may provide an alternate route to targeting NRAS-mutant melanoma." (PMID 36765834, 2023). "In conclusion, the combinatorial and sequential treatment of RAS/PI3K/RAF-targeted therapies after first-line immunotherapy may extend the anti-tumor response for TNBC and melanoma patients, especially those who harbor alterations in both the PI3K/AKT/mTOR and MAPK/MEK/ERK pathways." (PMID 35806358, 2022). "Treatment with mTOR pharmacological inhibitors as stand-alone therapy failed to provide long-lasting benefits in the majority of cancer patients, including those suffering from melanoma." (PMID 36077374, 2022). "MEK inhibitors for NF1-mutation melanoma: Although NF1-mutant melanoma patients do not usually express NRAS or BRAF mutations, inhibition of the BRAF, MEK and mTOR pathways may be therapeutic since the NF1 mutation increases RAS/MAPK pathway signalling." (PMID 36232957, 2022). "Although several studies have converged upon reactivation of the MAPK pathway as a relevant mechanism of acquired resistance in melanoma, our findings indicate that increased compensatory signaling through the PI3K/AKT/mTOR axis might be generally more determinant in driving late-stage resistance." (PMID 36434616, 2022). "Considering the overall implications of mTOR signaling in mediating IFN biological effects, it will be important to determine whether, in treatment-naïve melanoma patients, a high- or low intratumoral activity of mTORC1 or mTORC2 could help predict the therapeutic response to ICI." (PMID 36077374, 2022).
melanoma (continued). "In addition, hyperphosphorylation of mTOR at its threonine Thr2446 and serine residues (Ser2448 and Ser2481) occurred both via the EGFR-ERK-S6K1 axis and the PI3K/AKT axis and is related to growth in various types of cancers and melanoma." (PMID 35208960, 2022). "Thus, we hypothesized that PURPL intervenes in autophagy to modulate melanoma progression by directly interacting with ULK1 and mTOR." (PMID 34759263, 2021). "Taking into account the vital role of mTOR in the regulation of translation, we expected that inhibition of mTORC1 activity and RPS6 phosphorylation observed in melanoma cells in response to longer treatments might negatively affect the rates of protein synthesis." (PMID 32531927, 2020). "Even though the A375 melanoma cells were grown in full media, the PIKfyve inhibitor, as well as the pyridinyl imidazole compounds SB202190 and SB590885, all seemed to disrupt lysosomal mTOR targeting as the mTOR staining pattern changed from dot-like structures to diffuse cytoplasmic staining." (PMID 32531927, 2020). "Additionally, under normoxia, melanoma cells can regulate and stabilize HIF-1α at the translational level, through mTOR and melanoma antigen-11 (MAGE11), that is involved in the inhibition of prolyl hydroxylase domain protein 2 (PHD2), a HIF-1α negative regulator." (PMID 32528879, 2020). "Reports are suggesting that overactivation of the PI3K/AKT/mTOR pathway might contribute to the survival of melanoma cells upon BRAF V600E inhibition and that dual targeting of advanced human cancers with inhibitors of the PI3K/AKT/mTOR and RAF/MEK/ERK pathways might be beneficial." (PMID 32531927, 2020). "The herein reported nanomolar concentration of mTOR inhibitor everolimus in the combination with inhibitor of MAP kinase (AS-703026) or AKT kinase (MK-2206) pathway are sufficient to induce apoptosis, and reduce proliferation and invasiveness in melanoma cells." (PMID 30848427, 2019). "The use of a combination of mTOR inhibitor – rapamycin and AKT inhibitor – MK-2206 has been described by many research groups that reported a reduction of cell growth, blockade of cell cycle progression, and enhanced apoptosis in different melanoma models (humans, murine and canine)." (PMID 30848427, 2019). "The phosphatidylinositol 3-kinase (PI3K)/protein kinase B (AKT)/mammalian target of rapamycin (mTOR) and mitogen-activated protein kinase (MAPK) signaling pathways regulate cell survival, proliferation, migration and invasion, which are key functions of melanoma progression." (PMID 30866426, 2019). "We found decreased expressions of FAK, p-PI3K, p-Akt, and p-mTOR in A2058 and A375 cells after bornyl cis-4-hydroxycinnamate treatment, which suggested involvement of the FAK/PI3K/Akt/mTOR signaling pathways in the inhibitory effects of bornyl cis-4-hydroxycinnamate in malignant melanoma cells." (PMID 30042328, 2018). "In melanoma cell lines Nutlin-3a failed to inhibit mTOR and the cells underwent senescence, which could be converted to quiescence by combining Nutlin-3a and Rapamycin, which inhibited mTOR." (PMID 29805774, 2018). "Furthermore, downregulation of LKB1 in malignant melanoma specimen, which exhibit activated Akt and overexpression of PLD2, correlates with enhanced mTOR activity, indicating that the mechanism described in this study contributes to pathogenesis of malignant melanoma." (PMID 28649994, 2017). "Moreover, PTEN appeared to play a causal role in determining pharmacological interactions between pathway inhibitors, as genetic manipulation of PTEN expression in melanoma cell lines, dramatically altered the functional response to combined MEK/mTOR inhibition." (PMID 28220839, 2017).
melanoma (continued). "Furthermore, we found that cryptolepine targets mitochondrial dynamics and biogenesis in melanoma cells and that these effects were accompanied by activation of AMPKα1/2-LKB1, inhibition of mTOR signaling, and a reduction in the levels of c-Myc, SIRT1 and PGC-1α protein." (PMID 28473727, 2017). "In melanoma, metabolic rewiring for glycolysis may be driven by multiple signaling pathways, including BRAF-driven MAPK hyperactivation that negatively regulates OXPHOS and PI3K/AKT/mTOR/HIF1α signaling that positively regulates glycolysis." (PMID 29209327, 2017). "Basal level phosphorylation of GH-regulated intracellular signaling networks like JAK2, STATs 1, 3, 5, ERK1/2, SRC, AKT and mTOR in absence of externally added GH suggested the presence of an autocrine ligand-receptor loop existent and critical in these four melanoma cell lines." (PMID 28223541, 2017). "Although in vitro study has shown that ASCT2 antagonist BenSer can suppress melanoma cell proliferation via cell cycle arrest and mTOR inhibition, this compound is not yet available in the clinic and its toxicity is unknown." (PMID 29094484, 2017). "Indeed, in a melanoma cell model PI3K inhibition was recently shown to prevent the activation of mTOR and cellular proliferation, but Akt inhibition did not lead to the same effect." (PMID 28401064, 2017). "Overall, these results suggest that the sensitivity of BRAF-mutant melanoma cells to BRAF or MEK inhibitors is at least partly mediated by activation of the PI3K pathway and can be enhanced by combined inhibition of the BRAF/MEK and PI3K/mTOR signaling pathways." (PMID 26137449, 2015). "Combinations of the PI3K inhibitors LY294002 and wortmannin or the mTOR inhibitor rapamycin with the chemotherapeutics cisplatin or temozolomide lead to a significant 2- to 3-fold increase in melanoma cell apoptosis, but MAPK pathway inhibitors do not significantly increase chemosensitivity." (PMID 24647338, 2014). "Rapamycin is a mTORC1 blocker of the first generation, while everolimus (RAD001) and temsirolimus (CCI779) are considered agents of second generation, which allosterically inhibit the mTOR complex; these agents do not have high specificity in targeting melanoma tumor cells." (PMID 24899250, 2014). "To assess whether autophagy exerts a protective role on cisplatin-induced apoptosis irrespective of the nature of autophagy inducer, we co-treated Me21 melanoma cells with CCI-779, a more soluble ester of rapamycin, which is a well-known autophagic stimulus acting through mTOR inhibition." (PMID 23437349, 2013). "Here, in melanocytes and in melanoma cell lines, we have studied the phosphorylation status of key PKB, mTOR and MAPK pathway components downstream of PTEN, PIK3CA, NRAS and BRAF mutations to determine whether the activity of the signalling pathways correlates with the upstream mutation." (PMID 22475322, 2012). "We could detect activation of the mTOR and ERK signaling pathways in proliferating melanoma cells." (PMID 16255777, 2005). "However, pharmacogenomic profiling indicates that melanomas are not, in general, PTEN deficient and therefore would be unresponsive to mTOR inhibitors." (PMID 16255777, 2005). "Similarly, in BRAF-mutant melanoma, PDX models resistant to BRAF and MEK inhibitors exhibited alternative activation of the mammalian target of rapamycin (mTOR) pathway, suggesting that mTOR inhibitors could be a viable treatment option for these patients." (PMID 41050078, 2025). "The development of clinically relevant pharmacological inhibitors to block the function of both PI3K/AKT/mTOR and MAPK/MEK/ERK could provide new avenues for well-designed studies that assess the tolerability and efficacy of a new therapeutic approach for the treatment of melanoma." (PMID 38334632, 2024).
melanoma (continued). "Furthermore, several small-molecule and antibody-based inhibitors of IGF1R and the PI3K/AKT/mTOR pathway are currently being tested in the clinic, highlighting the potential translatability of combining these drugs with BRAF/MEK inhibitor therapy for the treatment of melanoma LMD." (PMID 38866016, 2024). "In addition, mTOR inhibitors may have potential anti-tumor properties for post-transplant patients with cSCC, which may partially explain the improved ORR for patients with cSCC compared to melanoma in our study." (PMID 38993910, 2023). "Extending clinical testing of familial melanoma cases of unknown etiology to additional targets from the PI3K/Akt family might support clinical management further, especially in the context of PI3K/Akt/mTOR inhibitors being actively considered as therapeutic approaches." (PMID 34067022, 2021). "Moreover, another mTOR inhibitor drug, Vistusertib, currently in phase II clinical trial for meningioma, was reported to have a positive impact by mTORC1/2 inhibition of the resistance to MAPK pathway inhibitors in melanomas with high oxidative phosphorylation." (PMID 32503412, 2020). "Accordingly, S6 phosphorylation dependent of melanoma-PD-1 could be reversed via specific inhibitor of mTOR but not PI3K, demonstrating that PD-1 receptor on surface of melanoma activates downstream mTOR signaling independent of PI3K to promote tumor proliferation." (PMID 30105035, 2018). "Thus, Ole, by affecting the PI3K/AKT/mTOR pathway, might represent a new non-toxic agent of interest in the treatment of advanced melanoma." (PMID 30544808, 2018). "Interestingly, treatment with rapamycin (a well known mTOR inhibitor and inducer of autophagy) only marginally increased autophagy in miR-638 depleted cells and completely failed to induce autophagy in control melanoma cells." (PMID 25650662, 2015). "Thus, by combined effect of mTOR inhibition and VEGF blockade on VEGFR2 and VEGFR3 signaling, the effect of this combination therapy may be explained in part by direct effects of both agents on melanoma cells." (PMID 24047116, 2013). "The pathogenesis of several solid human cancers including melanoma and non-melanoma cancers has been correlated with deregulation of the PI3K/Akt/mTOR pathways." (PMID 38182748, 2024). "The regulation of melanoma proliferation, metastasis and glycolysis by HK2 through the AKT/mTOR signalling pathway has not been reported." (PMID 37539493, 2023). "Melanoma EVs can stimulate melanoma cell growth by regulation of gene transcription by non-coding RNA and activation of the PI3K/AKT/mTOR pathway." (PMID 35327461, 2022). "While mTOR inhibition (PP242 and Everolimus) did not promote CD40 expression on melanoma cells, suppression of either MEK or AKT pathways, induced CD40 expression in BRAFmut YUMM3.3 cells." (PMID 34092233, 2021). "In melanoma, for example, when leucine is deprived, hyperactivation of RAS-MEK signaling fails to inhibit mTOR, thereby triggering apoptosis of human melanoma cells." (PMID 33849550, 2021). "In this study, we demonstrated that IQ promotes the mitochondrial apoptotic cell death of melanoma cells, particularly the SK-MEL-2, through the modulation of the PI3K/AKT/mTOR signaling pathway, without exhibiting cytotoxicity against normal skin cells." (PMID 33260329, 2020). "Melanoma tissues derived from patients treated with the temsirolimus (mTOR inhibitor) and bevacizumab (VEGF inhibitor) combination were used in this study and in particular, treated versus non-treated melanoma tissues were analyzed." (PMID 32013263, 2020). "To test this possibility, we first analyzed the phosphorylation and activation of mTOR and its downstream substrates p70S6K and 4E-BP1 in melanoma cells treated with or without baicalein and baicalin." (PMID 32984331, 2020).